ENSG00000268750 (novel protein)
Gene: Protein-coding gene on chromosome 19 (57,819,719 to 57,858,941, forward strand). Ensembl gene ENSG00000268750.
Genetic constraint (gnomAD): Loss-of-function variants: 1 observed, 2.2 expected, observed/expected ratio (o/e) 0.46, 90% interval 0.16 to 1.7. That is too few expected variants to judge how well the gene tolerates losing a copy. Missense variants: 48 observed, 78.74 expected, observed/expected ratio (o/e) 0.61, 90% interval 0.48 to 0.77. Synonymous variants: 20 observed, 30.06 expected, observed/expected ratio (o/e) 0.67, 90% interval 0.47 to 0.97.